MMP3 (matrix metallopeptidase 3)
Diseases named in the same sentence as MMP3 in open-access papers (continued):
Sharing a sentence is not in itself a finding about the gene and the disease.
Arthritis (continued). "In a murine type II collagen-induced arthritis, it was found that NF-kB expression correlated with MMP-13 and MMP-3 levels leading to cartilage destruction and articular damage." (PMID 22146575, 2011). "The selected proteins constitute inflammatory mediators and chemokines involved in arthritis, including TNF-α, IL-17, IL-6, MMP-3 and KC." (PMID 20731827, 2010). "In murine AIA, significant and temporal changes in cytokines (IL-1β, TNFα, IFN-γ, IL-6) and factors that govern extracellular matrix turnover (MMP-3, MMP-13, TIMP-1) occur during the acute phase, Days 1 to 3 after arthritis induction." (PMID 20307272, 2010). "It was found that HC could reduce foot swelling in CIA rats, lower the arthritis index, and decrease the secretion of MMP-2, MMP-3, TNF-α, and IL-6." (PMID 41508102, 2026). "The markers hs-CRP (high-sensitivity C-reactive protein), OPG (osteoprotegerin), and MMP-3 (Matrix Metalloproteinase-3) have been useful in distinguishing PsA patients from those with psoriasis without arthritis." (PMID 40284188, 2025). "Serum MMP-3 concentration and MSUS were helpful for the diagnosis of arthritis." (PMID 37336934, 2023). "As a result, the detection of active MMP-3, ADAMTS-5, and TIMP-3 in clinical samples could reveal information regarding the development of arthritis and the response to therapy." (PMID 37259405, 2023). "Serum concentrations MMP-1, MMP-3, and MMP-9, acutely adapt to mechanical loading, with rapid increases at the beginning of physical activity followed by a fairly rapid stabilization thereafter; moreover, MMP-2, MMP-3, and MMP-9 are highly expressed in patients afflicted by arthritis." (PMID 36835076, 2023). "WFR could effectively alleviate the arthritis symptoms of CIA rats; reduce the levels of IL-6, IL-1β, and TNF-α in the peripheral blood of CIA rats; and inhibit the expression of MMP3 and fibronectin." (PMID 38098062, 2023). "Other MMPs, such as MMP-3, are also elevated in arthritis, and these enzymes degrade non-collagenous matrix components of joints." (PMID 35924046, 2022). "However other studies indicated that in a mouse model of collagen-induced arthritis, adiponectin significantly reduced the severity of arthritis along with decreasing the expression of TNF-α, IL-1, and MMP-3 in joint tissues." (PMID 35628866, 2022). "MMP-3 is known to degrade CII, the predominant form of collagen in articular cartilage, whereby MMP-3 concentrations are elevated in serum of humans and mice with active arthritis." (PMID 35874732, 2022). "Treating the 5-mo-old DNase II−/−STINGS365A/S365A mice with anti–IL-6R reduced the arthritis score and the expression of IL-6 and MMP-3 but did not reduce the expression of TNF-α, CXCL1, and CXCL2." (PMID 34901991, 2022). "When calcitriol is used in the treatment of knee osteoarthritis, it can inhibit MMP by inhibiting MMP-1, MMP-3, and MMP-13 gene expression, thereby reducing the severity of arthritis in patients, reducing pain in patients, and improving the living conditions of patients." (PMID 36091601, 2022). "MMP3 is a member of the MMP family, which is widely involved in the breakdown of extracellular matrix proteins during tissue remodeling, such as embryonic development and reproduction, as well as in disease processes, such as arthritis and tumor metastasis." (PMID 34198485, 2021). "Unfortunately, no data were available for MMP-3, ferritin, or the IL-18 level in one interval fever-onset patient with methotrexate-dependent arthritis (#25)." (PMID 34354966, 2021). "Thus, SFs explant cultures from animals undergoing experimental arthritis were examined for ARNO-dependent expression of IL-6, CCL2 and MMP3." (PMID 35095899, 2021). "We assessed whether changes in the levels of the objective biomarkers of arthritis (serum CRP, MMP-3) after ABA treatment for 24 weeks were different between the Th17.1-lower and Th17.1-higher groups." (PMID 31747403, 2019).
Arthritis (continued). "Furthermore, a function study reported that the S100A8 stimulation in chondrocytes induces upregulation of mRNA levels of MMP-2, MMP-3, MMP-9, and MMP-13 and ADAMTS-4 and ADAMTS-5 in experimental murine arthritis, which is similar to our findings." (PMID 31815654, 2019). "An early upregulation of MMP-3 and MMP-9 activities has been described in TNF-overexpressing mice that develop arthritis, also implying that FLS activation is an early event in arthritis pathogenesis and supporting our findings." (PMID 30466479, 2018). "MMP-3-deficient mice develop arthritis in a CIA model, and disruption of MMP-3 gene does not prevent cartilage destruction." (PMID 28441353, 2017). "Interestingly, the in vivo imaging data were corroborated by correspondingly increased MMP3 serum levels, consistent with our observation that polybacterial-infected mice with CIA developed more severe clinical arthritis." (PMID 27405639, 2016). "Bone destruction (MMP3 serum levels, cathepsin B activity, and RANKL mRNA) peaked at day 3 after arthritis induction, followed by a peak in cartilage destruction and bone erosion on day 5 after arthritis induction." (PMID 26801240, 2016). "In line with the arthritis scores and the pro-inflammatory cytokine profile, histological signs of arthritis, macrophage infiltration and Mmp3 expression were largely decreased in the absence of Aim2." (PMID 26114879, 2015). "Induction of arthritis in HO-1−/− mice but not in HO-1+/− animals significantly increased serum levels of MMP-3, PAI-1, E-selectin and ICAM-1 whereas VEGF levels were lower than those of HO-1+/+ or HO-1+/− mice." (PMID 23285041, 2012). "We hypothesize that the addition of HA will alleviate inflammatory nociception and impede the accumulation of arthritis-induced HIF-1α, iNOS, and MMP3 production in the early phase of the experimental arthritic inflammatory joint." (PMID 21679445, 2011). "The serum concentrations of MMP3 were above the detection limit in 30 out of 30 samples from the normal iron diet group and in 27 out of 28 samples from the low iron diet group (and in all samples from both diet groups without arthritis induction)." (PMID 39513899, 2024). "Similarly, pharmacological inhibition of the LPA1 receptor by Ki16425 in the K/BxN serum-transfer arthritis model led to a reduction in arthritis severity by decreasing cartilage damage, bone erosion, and expression of RANKL, ITAC/CXCL11, Pro-MMP9, and MMP3, in mouse arthritic joints." (PMID 35408784, 2022). "In the DBA/1 mouse model of collagen-induced arthritis, adiponectin treatment significantly alleviated the severity of arthritis together with a decrease in the expression of pro-inflammatory cytokines such as TNF-α and IL-1, and the reduction of metalloproteinase (MMP)-3 in synovial tissues." (PMID 32362840, 2020). "MMP-3 may therefore be a biomarker more specific to peripheral synovial-based arthritis, than to axial non-synovial entheseal-based arthritis." (PMID 28934972, 2017). "Although this was demonstrated in an arthritis model, it is possible that this mechanism is used in different disease states including BC such that fibronectin fragments generated by PIP activity may also upregulate the expression of MMP3 and MMP13 in the 4T1-PIP tumors." (PMID 33777801, 2021). "In PsA, integrating biomarkers such as MMP-3, COMP, and genetic factors like HLA-B27 and HLA-C06 improves differentiation between PsA and psoriasis without arthritis." (PMID 40095875, 2025). "The MMP-3 and VEGF concentrations were greater in YP with JIA with WBMRI-detected joint inflammation than in those without, respectively (available at Rheumatology online)." (PMID 38244609, 2024). "In addition, the expression of other MMPs, such as MMP-2, MMP-3, and MMP-9, is elevated in arthritis, and these enzymes degrade non-collagen matrix components of joints." (PMID 34209006, 2021).
Arthritis (continued). "Evaluation of the MMP-3 concentration and MSUS findings, particularly enhanced PD signals on periarticular soft tissue, joint fluid, and edematous thickening of synovium without PD signals, may help to diagnose arthritis in patients with poor findings." (PMID 37336934, 2023).
melanoma (49 papers, 1999 to 2026). A malignant, usually aggressive tumor composed of atypical, neoplastic melanocytes. "In this respect, the aim of the current pilot study was to identify MMP3 -1171insA genotype frequency and to evaluate its impact on the susceptibility to coetaneous malignant melanoma in a Bulgarian population from Stara Zagora region." (PMID 26019576, 2014). "We evaluated MMP2 and MMP3 germline polymorphisms in a group of 1002 melanoma patients using PCR-based methods, including fragment size analysis and melting temperature profiles." (PMID 17958893, 2007). "Functional promoter polymorphisms in MMP2 and MMP3 genes were examined in a cohort of 1002 melanoma patients." (PMID 17958893, 2007). "This study does not provide strong evidence for further investigation of MMP2 and MMP3 genetic variants in melanoma progression." (PMID 17958893, 2007). "This study does not provide strong evidence for further investigation into the role of the MMP2 and MMP3 variants in melanoma progression." (PMID 17958893, 2007). "The MMP3 allele with high transcriptional activity 5A was found more frequently in patients with melanomas containing infiltrating lymphocytes and showing low Clark level lesions." (PMID 17958893, 2007). "Moreover, MMP3 expression was associated with the enrichment of tumor-associated macrophages (TAMs), which are believed to be essential in the development of melanoma brain metastasis." (PMID 39157383, 2024). "The down-regulation of MMP-3 and miR-214 might be associated with the anti-metastatic property of rCTII in melanoma." (PMID 33167431, 2020). "This is particularly relevant in cases where elevated levels of MMP-3 are correlated with an increased incidence of experimental lung metastases in melanoma." (PMID 39769318, 2024). "For instance, there is evidence suggesting that MMP-3 plays a significant role in the development of the malignant phenotype of melanoma." (PMID 39769318, 2024). "A possible similar activation of keratinocytes surrounding melanoma has been suggested by in vitro evidence that medium conditioned by melanoma cells stimulates the production of MMP3, MMP9, and MMP14 by Hacat cells while lowering TIMP expression." (PMID 38473275, 2024). "In our study, treatment with the IκB kinase inhibitor TPCA-1 resulted in the inhibition of IL-1β-induced MMP-3 mRNA expression and protein release in melanoma cells." (PMID 36445856, 2022). "We observed that a dose-dependent upregulation of MMP-3 release in culture media of melanoma cells stimulated with IL-1β at the range of 0 to 100 pM for 24 h." (PMID 36445856, 2022). "MMP3 is known to be expressed by keratinocytes and to support melanoma metastasis formation, however its elevated expression in CAKs was not described before." (PMID 36123693, 2022). "Then we evaluated the effect of IL-1β on MMP-3 mRNA expression in p65/RelA- or p105-depleted melanoma cells." (PMID 36445856, 2022). "Experimental metastasis and cell growth were significantly increased in nude mice injected with human melanoma cells overexpressing MMP-3 but were inhibited in nude mice injected with MMP-3-silenced melanoma cells." (PMID 36445856, 2022). "MMP-3 protein expression and release in human melanoma have been observed in aggressive and highly metastatic cell lines." (PMID 36445856, 2022). "In the present study, we showed that NF-κB p65/RelA contributes to MMP-3 expression induced by IL-1β in melanoma cells." (PMID 36445856, 2022). "In the present study, we demonstrated that IL-1β triggers MMP-3 expression and release in canine melanoma cells." (PMID 36445856, 2022). "In the present study, we demonstrate that the canonical NF-κB signaling pathway, NF-κB p65/RelA activation, is involved in the IL-1β mediated-MMP-3 expression in canine melanoma cells." (PMID 36445856, 2022).
melanoma (continued). "When canine melanoma cells were stimulated with IL-1β at the concentration of 100 pM for 0–48 h, the activity of MMP-3 in the culture media supernatant was increased, which implies IL-1β-stimulated MMP-3 release." (PMID 36445856, 2022). "In this study, released MMP-3 was found to mediate the migration of melanoma cells in an autocrine manner." (PMID 36445856, 2022). "Taken together, MMP-3 plays an important role in the cellular migration of IL-1β-treated melanoma cells via protease activity." (PMID 36445856, 2022). "MMP-3 deficiency in melanoma is reported to reduce the formation of 3D-tumoroids in vitro, whereas the addition of MMP-3-enriched extracellular vesicles promotes the tumorigenicity and proliferation of MMP-3 (-/-) melanoma cells." (PMID 36445856, 2022). "As MMP-3 expression is observed in various types of malignant cells, including human malignant melanoma, MMP-3 has been considered to play a role in malignant processes." (PMID 36445856, 2022). "Studies have reported that NFAT1 promotes melanoma metastasis by regulating autotaxin, IL-8 and MMP3 expression." (PMID 35081978, 2022). "In the interleukin-4 and interleukin-13 signaling pathway, CXCL8 and MMP3 have published roles in melanoma growth and metastasis." (PMID 35008167, 2021). "This is consistent with other reports linking MMP-3 to invasion and metastatic potential of melanoma cell lines and shorter disease-free survival." (PMID 32455575, 2020). "MMP-9 and MMP-3 were mainly expressed by keratinocytes whereas TIMP-1 was mainly expressed by Tspan8+ melanoma cells." (PMID 32455575, 2020). "Together, these data indicated the role of M/Ms in melanoma brain metastasis and suggested that MMP3 of M/Ms related pathway is a promising therapeutic target." (PMID 30616691, 2019). "Here, with long-term intravital microscopic imaging, we identified that the M/Ms were persistently activated with distinct cellular dynamics and facilitated the formation of melanoma brain metastasis, which were highly correlated with their MMP3 expression." (PMID 30616691, 2019). "Then, to explore if the MMP3 expressed by M/Ms disrupted the tight junction of the BBB to promote brain metastasis of melanoma cells, the tight junction protein ZO-1 was detected via immunofluorescence staining." (PMID 30616691, 2019). "Taken together, these results demonstrated that the facilitation of melanoma brain metastasis formation by M/Ms was partially due to the crucial role of MMP3 in BBB impairment." (PMID 30616691, 2019). "In vivo experiments consistently demonstrated that the silencing of MMP3 expression led to reduced tumor growth and metastatic potential of melanoma cells." (PMID 31304688, 2019). "Data from a recent publication have also demonstrated that NFAT1 promotes melanoma tumor growth and metastasis via direct regulation of IL-8 and MMP-3." (PMID 30459241, 2018). "A recent study has demonstrated that NFAT1 promotes melanoma tumor growth and metastasis via direct regulation of IL-8 and matrix metalloproteinase (MMP)-3 (MMP-3)." (PMID 30459241, 2018). "MMP1, MMP2 and MMP3 are known to be essential proteases for both the growth and metastatic spread of melanoma tumors." (PMID 28146421, 2017). "Thereafter, increased mRNA levels of MMPs were reported in TCDD-treated human cells, such as, MMP1 in keratinocytes and melanoma cells, MMP2 in melanoma cells, MMP3 and MMP7 in endometrial cells, and MMP9 in prostate cancer cells and melanoma cells." (PMID 16704738, 2006). "Serpinh1 is a protein playing a role in collagen biosynthesis, that enhances the malignancy in osteosarcoma, but its role in melanoma is not well understood, while osteopontin and Mmp3 are involved in cell adhesion, migration and in vivo tumor growth of melanoma." (PMID 39457009, 2024). "Also in agreement with our study, MMP3 was reported to be involved in premetastatic remodeling of lung blood vessels and escape of circulating tumor cells in a murine melanoma tumor model." (PMID 37903851, 2023).
melanoma (continued). "Here, we report that interleukin-1β (IL-1β) triggers the MMP-3 expression in canine melanoma cells." (PMID 36445856, 2022). "IL-1β was demonstrated to mediate MMP-3 expression and release in melanoma cells." (PMID 36445856, 2022). "The activity of MMP-3 in the culture supernatant was increased in IL-1β-treated melanoma cells." (PMID 36445856, 2022). "Interestingly, we observed the significant attenuation in MMP-3 mRNA expression in p65/RelA-depleted melanoma cells compared to p105 siRNA or the control scramble siRNA-transfected cells." (PMID 36445856, 2022). "Therefore, the relationship between p65/RelA and such transcription factors must be determined to elucidate the expression of MMP-3 via activation of NF-κB p65/RelA in canine melanoma cells." (PMID 36445856, 2022). "We have reported that treating melanoma cells with rCTII can remarkably reduce the expression level of MMP-3, which may have an important role in the suppression of the metastasis." (PMID 33167431, 2020). "We also investigated the correlation of the seven prognostic-associated TBCs between MMP-related genes (MMP2, MMP9, MMP7, MMP14, BSG, EGFR, MMP1, MMP3) and EMT-associated genes (TWIST1, VIM, CDH2, ACTA2, ZEB1), which also indicated a central role of TBCs in melanoma." (PMID 33194704, 2020). "Importantly, MMP-3 full activation is Tspan8-dependent as SR generated with non-invasive melanoma cells ectopically expressing Tspan8 acquired the property to produce a large amount of fully active MMP-3." (PMID 32455575, 2020). "Moreover, we demonstrated that these activated M/Ms facilitated melanoma brain metastasis in vivo, which were highly correlated with their MMP3 expression." (PMID 30616691, 2019). "Hence, these results indicated that the tight junction of the BBB was gradually disrupted during the formation of melanoma brain metastasis, which is possibly attributed to the MMP3 in M/Ms." (PMID 30616691, 2019). "An MMP inhibitor moderately decreased the occurrence of melanoma brain metastasis, suggesting that MMP3 secreted by M/Ms may facilitate melanoma cell growth." (PMID 30616691, 2019). "To determine whether MMP-cleaved OPN has cell adhesion ability, we used a B16-BL6 mouse melanoma cell adhesion assay with OPN or OPN treated with MMP-3 or -7." (PMID 25545242, 2014). "Thus, IL-1β mediates the MMP-3 expression and release in canine melanoma cells." (PMID 36445856, 2022). "Furthermore, rCTII has down-regulated the expression levels of miR-214 and MMP-3, which may inhibit metastasis in melanoma." (PMID 33167431, 2020). "Since we showed a greater inhibitory effect of the FB/SFN combination on cell migration in the metastatic WM266-4 cell line, we evaluated if SFN and FB could alter the production of collagenase MMP-1, gelatinases MMP-2 and MMP-9 and stromelysin MMP-3 in this melanoma cell line." (PMID 32486135, 2020). "Thus, snake venom toxins, e.g., rCTII, can down-regulate MMP-3 and may suppress metastasis in tumoral cells, especially in melanoma." (PMID 33167431, 2020). "Among the genes downregulated by melanoma-derived SPN, MMP-1, MMP-3, and MMP-12 showed similar expression patterns in both NHFs and CAFs." (PMID 40869222, 2025). "Prominent MMPs, including MMP-1, MMP-2, MMP-3, MMP-9, MMP-13, and MMP-14, have been shown to significantly contribute to the development of melanoma." (PMID 39769318, 2024). "Immunomodulatory CAFs (iCAFs) displayed high expression of MMP1, MMP3, IL6, CXCL8, and IDO1, and included CAFs from melanomas, 1 SCC, and 1 BCC." (PMID 38525245, 2024). "For example, a study analyzing the expression of MMPs in melanoma found that MMP-1, MMP-2, MMP-3, MMP-7, MMP-9, and MMP-13 showed increased levels in melanoma tissues compared to normal tissues." (PMID 39200315, 2024). "In our study, an MMP-3 inhibitor significantly inhibited IL-1β-mediated melanoma cell migration, supporting the role of MMP-3 in melanoma metastasis." (PMID 36445856, 2022).